MTAP (methylthioadenosine phosphorylase)
Diseases named in the same sentence as MTAP in open-access papers (continued):
Sharing a sentence is not in itself a finding about the gene and the disease.
thymic carcinoma (5 papers, 2022 to 2025). Thymic carcinoma (TC) is a type of thymic epithelial neoplasm characterized by a high malignant potential. "Overall, our study suggested that loss of cytoplasmic mTAP expression is a predictor of thymic carcinoma even though its sensitivity is low." (PMID 35565429, 2022). "We aimed to determine the prognostic significance of CD5, CD117, EZH2, POU2F3, BAP1, and MTAP immunohistochemical staining in thymic carcinomas." (PMID 40242668, 2025). "We recently showed that a panel of CD117, BAP1, mTAP, and TdT was able to predict 89% of thymic carcinomas and 78% of type A and B3 thymomas and MNTLS, leaving room for improvement in immunohistochemical panels for this differential diagnosis." (PMID 37190202, 2023). "We found that a panel of CD117 with a cut-off of 10% tumor cell expression, BAP1, mTAP, and TdT was able to predict 88.9% of thymic carcinomas and 77.8% of thymomas (among the studied types A and B3 thymomas and micronodular thymomas with lymphoid stroma)." (PMID 35565429, 2022). "Loss of expression of BAP1 and mTAP was observed in a subset of thymic carcinomas but not in thymomas." (PMID 35565429, 2022). "A large subset of thymic carcinomas (88.9%) could be predicted using a combination of loss of BAP1 and/or mTAP expression and/or expression of CD117 in ≥10% of tumor cells." (PMID 35565429, 2022). "We explored the relationship between CD5, CD117, EZH2, POU2F3, MTAP, and BAP1 immunoreactivity and the overall survival (OS) and progression-free survival (PFS) of patients with thymic carcinoma, using a cohort with diverse histologic subtypes." (PMID 40242668, 2025). "CD5, CD117, EZH2, POU2F3, MTAP, and BAP1 have been proposed as useful markers for the distinction of thymic carcinoma from thymoma." (PMID 40242668, 2025). "Recently, researchers of the Mayo Clinic (Rochester, MN, USA) used a panel of CD117, BAP1, mTAP and TdT in a series of 81 TETs including 44 thymomas and 37 thymic carcinomas and concluded that this panel could be useful to distinguish thymomas from thymic carcinomas." (PMID 37240815, 2023). "Our study showed that a panel of IHC markers, including BAP1, mTAP, CD117, and TdT can aid in predicting the vast majority of thymic carcinomas and epithelial cell-rich thymomas, including types A and B3 thymomas and MNTLS." (PMID 35565429, 2022). "In this series of 81 TET, including 37 thymic carcinomas and 44 thymomas (including type A and B3 thymomas and MNTLS) we have shown that a panel of CD117, BAP1, mTAP, and TdT can correctly predict 88.9% of thymic carcinomas and 77.8% of thymomas." (PMID 35565429, 2022). "Whole slide sections of 37 thymic carcinomas, 23 type A thymomas, 13 type B3 thymomas, and 8 micronodular thymomas with lymphoid stroma (MNTLS) were immunostained for EZH2, POU2F3, CD117, CD5, TdT, BAP1, and MTAP." (PMID 37190202, 2023). "None of the thymic carcinomas showed loss of either marker except for one adenocarcinoma in which tumor cells showed loss of expression of BAP1 and a subset of tumor cells also showed loss of expression of mTAP." (PMID 35565429, 2022). "Expression of BAP1 and mTAP have not been studied in TET, but the molecular studies suggest that those markers could be useful in the distinction between thymomas and thymic carcinomas." (PMID 35565429, 2022). "Overall, only 11.1% of thymic carcinomas and 22.2% of thymomas could not be predicted using a panel of BAP1, mTAP, CD117, and TdT." (PMID 35565429, 2022).
urothelial bladder cancer (5 papers, 2016 to 2025). "Our data demonstrate a high homogeneity of MTAP deficiency in advanced urothelial carcinomas of the urinary bladder." (PMID 40664803, 2025). "Among 41 consecutive primary pT2-4 urothelial bladder carcinomas from which 1–15 (average 6.4) whole sections were analyzed, MTAP was homogeneously deficient in 34.1%, heterogeneously deficient in 4.9% and homogeneously retained in 61.0%." (PMID 40664803, 2025). "Therefore, inhibition of enzymes critical for folate synthesis leads to increased apoptosis of MTAP-deficient tumor cells in experimental models and shows anti-cancer efficiency in patients with urothelial bladder carcinomas." (PMID 40227771, 2025). "Drugs targeting MTAP deficiency could be highly useful in a relevant subset of invasive urothelial bladder cancers." (PMID 40664803, 2025). "The results of this study identify about 25% of urothelial carcinomas of the urinary bladder as MTAP‐deficient and demonstrate that MTAP deficiency goes along with a noninflamed tumor microenvironment, aggressive tumor phenotype, and poor patient prognosis in muscle‐invasive disease." (PMID 39668577, 2025). "Drugs targeting MTAP‐deficiency may be useful in urothelial bladder carcinoma." (PMID 39668577, 2025). "A tissue microarray including 2,710 urothelial bladder carcinomas were analyzed for 9p21 deletion by fluorescence in situ hybridization and MTAP expression by IHC." (PMID 39668577, 2025).
esophageal cancer (4 papers, 2022 to 2024). A primary or metastatic malignant neoplasm involving the esophagus. "In esophageal cancer, MTAP depletion can activate the GSK3/Slug/E-cadherin axis, promoting migration and invasion." (PMID 36913304, 2023). "Knockdown of MTAP can activate the GSK3β/Slug/E-cadherin axis and promote migration and invasion in esophageal cancer." (PMID 35541910, 2022).
fibrosarcoma (4 papers, 2014 to 2022). A malignant mesenchymal fibroblastic neoplasm affecting the soft tissue and bone. "In the experiments described here, we have characterized the phenotype of an MTAP-deleted HT1080 human fibrosarcoma cell line in which we have stably reintroduced the MTAP gene." (PMID 25387827, 2014). "Furthermore, MTAP reintroduced into MTAP-deleted HT1080 fibrosarcoma cells resulted in a variety of phenotypes and gene expression, which was involved in Wnt or other signaling pathways." (PMID 31965001, 2020). "HT1080 cells are an immortalized human fibrosarcoma cell line that lacks MTAP expression." (PMID 25387827, 2014). "In our initial examination of MTAP status and protein sDMAylation, we utilized a pair of isogenic MTAP+ and MTAP-deleted HT1080 fibrosarcoma cell lines (referred to HTM+ and HTM−) that our laboratory has previously generated." (PMID 35963436, 2022).
malignant peripheral nerve sheath tumor (4 papers, 2016 to 2025). Malignant peripheral nerve sheath tumor (MPNST) is a rare and often aggressive soft tissue sarcoma occurring in a wide range of anatomical sites. "MTAP had CNLs in approximately 60% cases in malignant peripheral nerve sheath tumor cohort from MSKCC." (PMID 27929028, 2016).
metastatic melanoma (4 papers, 2016 to 2024). A melanoma that has spread from its primary site to another anatomic site. "In order to detect the MTAP-ANRIL fusion gene transcript, we screened 174 metastatic melanoma cell lines for the deletion at the locus." (PMID 26909863, 2016).
metastatic tumors (4 papers, 2021 to 2026). "The mutational frequencies of CDKN2B (14.8% vs. 0%, p = 0.001), FAT3 (7.4% vs. 0%, p = 0.041), MTAP (13% vs. 1.6%, p = 0.023), and SMAD4 (31.4% vs. 15.6%, p = 0.049) in metastatic tumors were significantly higher than that in primary tumors." (PMID 35664782, 2022). "We believe our findings will encourage future clinical trials examining MAT2A inhibitors in MTAP-deleted NPC, including recurrent and metastatic diseases, which are often deadly." (PMID 34234122, 2021). "The mutational frequencies (metastatic vs. primary) of CDKN2B (14.8% vs. 0%, p = 0.001), FAT3 (7.4% vs. 0%, p = 0.041), MTAP (13% vs. 1.6%, p = 0.023), and SMAD4 (31.4% vs. 15.6%, p = 0.049) in metastatic tumors were significantly higher than in primary tumors." (PMID 35664782, 2022). "Importantly, the mutational frequency of CDKN2B (14.8% vs. 0%, p = 0.001), FAT3 (7.4% vs. 0%, p = 0.041), MTAP (13% vs. 1.6%, p = 0.023), and SMAD4 (31.4% vs. 15.6%, p = 0.049) in metastatic tumors were significantly higher than those in primary tumors." (PMID 35664782, 2022). "In Patient 3, three genomic loci—9p21 (CDKN2A and MTAP), 11q13 (OVOL1), and 11p15 (HRAS)—were homozygously deleted in the primary site tumor population (3PST) but not in the metastatic tumor population (3MT)." (PMID 40004220, 2025).
pancreatic ductal adenocarcinoma (4 papers, 2024 to 2026). An infiltrating adenocarcinoma that arises from the epithelial cells of the pancreas. "We assessed the significance of MTAP loss across 1545 resected tumors (cholangiocarcinoma, esophageal and gastric adenocarcinoma, pancreatic ductal adenocarcinoma)." (PMID 42129334, 2026). "The high rate of homogeneous MTAP deficiency in ductal adenocarcinomas of the pancreas is of clinical importance." (PMID 40227771, 2025). "The high rate of homogeneous MTAP deficiency in ductal adenocarcinomas of the pancreas is of potential clinical significance." (PMID 40227771, 2025). "The results of this study identify 37.9% of our primary ductal adenocarcinomas of the pancreas as MTAP-deficient." (PMID 40227771, 2025). "Loss of MTAP expression is frequent, mostly homogenous, and always caused by homozygous 9p21 deletion in pancreatic ductal adenocarcinomas." (PMID 40227771, 2025). "Furthermore, we identified ductal adenocarcinoma of the pancreas as one of the most common MTAP-deficient cancers, with an MTAP loss rate of approximately 30%." (PMID 40227771, 2025). "Other studies had reported MTAP deficiency by IHC in 27–30% and deep deletions by next-generation sequencing (NGS) in 2–21% of ductal adenocarcinomas of the pancreas." (PMID 40227771, 2025).
renal cell carcinoma (4 papers, 2019 to 2024). "Ching-Hsien Chen of the University of California Davis and colleagues in the USA and Taiwan found that renal cell carcinomas are deficient in the enzyme methylthioadenosine phosphorylase (MTAP)." (PMID 30701095, 2019).
T-cell lymphoma (4 papers, 2013 to 2023). "Mice heterozygous for a germline mutation in the mouse MTAP gene (Mtap) die prematurely of T-cell lymphoma with a mean age of onset of about 18 months." (PMID 23840755, 2013). "Although mice heterozygous for germline MTAP mutations did not fully recapitulate the genetic events in clinical specimens, they were prone to developing T-cell lymphomas; however, homozygous inactivation was embryonically lethal in the MTAP-knockout murine model." (PMID 25426549, 2014). "Our previous study showed that PDX was even more effective than MTX in the treatment of CEM T-cell lymphoma that lacked MTAP." (PMID 25917288, 2015). "However, in knockout mice heterozygous for MTAP appear to be indistinguishable from WT mice, but died because of T-cell lymphoma." (PMID 37894345, 2023).
triple-negative breast carcinoma (4 papers, 2023 to 2025). An invasive breast carcinoma which is negative for expression of estrogen receptor (ER), progesterone receptor (PR), and human epidermal growth factor receptor 2 (HER2). "Compared with triple-negative breast cancer, MTAP expression level is upregulated in Luminal A subtype, indicating MTAP deficiency observed in more malignant tumor subtypes." (PMID 37091983, 2023). "Similarly, the reduced expression of MTAP in triple-negative breast cancer could serve as both a diagnostic and therapeutic marker." (PMID 36913304, 2023).
breast adenocarcinoma (3 papers, 2013 to 2022). "Re-expression of MTAP protein in MTAP-deleted MCF-7 breast adenocarcinoma cells results in loss of anchorage independent growth in vitro and the ability to form tumors when injected into SCID mice." (PMID 23840755, 2013). "We next examined the effect of MTAP on protein sDMAylation in an MCF-7 breast adenocarcinoma-derived cell line in which MTAP under control of a doxycycline (Dox)-induced promoter." (PMID 35963436, 2022). "Previously, our group reported that expression of MTAP in MCF-7 breast adenocarcinoma cells also repressed soft agar growth and tumor formation in mice." (PMID 25387827, 2014).
ovarian carcinoma (3 papers, 2019 to 2020). A malignant neoplasm originating from the surface ovarian epithelium. "We also found that MTAP was downregulated in seven ovarian tumor samples as compared with the paired normal tissues by western blotting, which correlated well with our results that HSP60 downregulation in ovarian cancer cells led to increase expression of MTAP." (PMID 31477750, 2019).
sarcomatoid mesothelioma (3 papers, 2022 to 2024). A diffuse malignant mesothelioma arising from the pleura and less often the peritoneum. "In more than 90% of cases, sarcomatoid mesothelioma is found to have a CDKN2A homozygous deletion or loss of methylthioadenosine phosphorylase gene (MTAP), and in most cases, co-deletion is seen." (PMID 39409190, 2024). "In the same way, immunohistochemistry for MTAP or homozygous deletion of 9p21 (CDKN2A) in FISH is useful mainly in sarcomatoid mesothelioma that exhibit these losses in >80% of cases." (PMID 35204459, 2022).
thymoma (3 papers, 2022 to 2023). A neoplasm arising from the epithelial cells of the thymus. "Results for CD117, CD5, BAP1, MTAP, and TdT are similar to those previously published, as 32 out of 37 carcinomas and all thymomas in the present study were included in the prior study." (PMID 37190202, 2023). "While we did not perform CDKN2A FISH in B3 thymomas, none of the B3 thymomas in our study showed loss of mTAP expression, although the number of cases was relatively small." (PMID 35565429, 2022).
urothelial neoplasm (3 papers, 2025). A neoplasm involving a urothelium. "Both our FISH and IHC data suggest a role for MTAP deficiency in grade and stage progression of urothelial neoplasms." (PMID 39668577, 2025). "Given that MTAP expression was always strong in normal (non‐neoplastic) urothelium, and that complete MTAP expression loss was strictly limited to subsets of urothelial neoplasms, complete loss of MTAP expression can be considered a reliable marker for neoplastic urothelium." (PMID 39668577, 2025). "As we are using MTAP IHC in our routine work-up of newly diagnosed urothelial neoplasms we do regularly see such MTAP status heterogeneity in dysplastic flat lesions and in pTa tumors." (PMID 40664803, 2025). "Although not all patients with urothelial neoplasia can benefit from MTAP IHC, this approach appears to be highly useful in subsequent biopsies or cytological samples of patients with a previously diagnosed MTAP‐deficient urothelial neoplasm." (PMID 39668577, 2025).
acute myeloid leukaemia (2 papers, 2024 to 2025). "Although MTAP enzyme deficiency has been documented in acute myeloid leukaemia (AML), deletions of the MTAP gene have not been identified in this haematological malignancy." (PMID 39259513, 2024).
brain tumors (2 papers, 2023 to 2024). "In this context, we have established a new model called MTAP to enable a highly accurate diagnosis of brain tumors." (PMID 38483711, 2024). "The MTAP model represents the potential power of using artificial intelligence in brain tumor classification." (PMID 38483711, 2024). "The MTAP model introduces a novel classification strategy for brain tumors, leveraging the strength of deep learning methods and novel model refinement techniques." (PMID 38483711, 2024).
diffuse astrocytoma (2 papers, 2020 to 2024). A low-grade (WHO grade II) astrocytic neoplasm. "In recent years, MTAP was reported as a useful immunohistochemical surrogate marker for CDKN2A-HD in adult-type infiltrating diffuse astrocytoma (sensitivity: 88.2%, specificity: 98.3%)." (PMID 39117984, 2024).
malignant fibrous histiocytoma (2 papers, 2016 to 2017). "Mutations in MTAP may result in diaphyseal medullary stenosis with malignant fibrous histiocytoma (DMS-MFH), an autosomal-dominant syndrome characterized by bone dysplasia, myopathy, and bone cancer." (PMID 26672768, 2016).
malignant glioma (2 papers, 2021 to 2026). A grade III or grade IV glioma arising from the central nervous system. "Homozygous deletion of the methylthioadenosine phosphorylase (MTAP) gene occurs in 10-15% of all human cancers and up to 50% of high-grade malignant gliomas, representing one of the largest opportunities for precision oncology." (PMID 42150143, 2026). "In homozygous MTAP-deleted tumors, the residual MTAP staining is restricted to stromal cells (no MTAP staining in malignant glioma cells), predominantly of myeloid origin (IBA1-positive)." (PMID 34244484, 2021). "This is because human GBM tumors are comprised of a mix of malignant glioma (cancer) cells with genetic alterations like homozygous MTAP-deletion and non-transformed non-malignant stromal cells (e.g., myeloid cells)." (PMID 34244484, 2021). "Thus, a homozygous MTAP-deleted GBM tumor is an admixture of non-malignant MTAP-expressing stroma and MTAP-null malignant glioma cells." (PMID 34244484, 2021).
myeloma (2 papers, 2019 to 2021). "Importantly, we found that some of the genes (i.e., MAT2A, AHCY, MTR and MTAP) were upregulated in MGUS and smouldering myeloma patients as compared to healthy individuals." (PMID 33579905, 2021).
myocardial infarction (2 papers, 2016 to 2025). Gross necrosis of the myocardium, as a result of interruption of the blood supply to the area, as in coronary thrombosis. "MTAP demonstrated robust genetic support for CAD and related cardiovascular traits, with very strong associations for blood pressure (HuGE scores: SBP=83.89, DBP=56.10) and hypertension (HuGE=45.00) and significant associations with CAD (HuGE=20.00) and myocardial infarction (HuGE=20.00)." (PMID 41332607, 2025).